PODNL1 (podocan like 1)
Diseases named in the same sentence as PODNL1 in open-access papers:
PODNL1 is named in the same sentence as 30 diseases in open-access papers, as found by Europe PMC text mining. Sharing a sentence is not in itself a finding about the gene and the disease. The quoted sentences say what the papers report.
glioma (4 papers, 2020 to 2024). A benign or malignant brain and spinal cord tumor that arises from glial cells (astrocytes, oligodendrocytes, ependymal cells). "Previous studies have shown that PODNL1, a member of the small leucine-rich proteoglycan family, is a potential tumor matrix-mediated biomarker and is strongly associated with glioma prognosis." (PMID 39935693, 2024). "First, glioma tissues and patients' outcomes in our single center should be collected to further confirm the association between PODNL1 and overall survival." (PMID 33033506, 2020). "Although these results suggest that PODNL1 is a biomarker for glioma, the biological functions and the underlying mechanism of PODNL1 in glioma remain unknown." (PMID 33033506, 2020). "In particular, SLRPs have a class V member, named podocan-like 1 (PODNL1), which is found to be highly expressed in bone, glioma, bladder and ovarian cancers, representing a potential prognostic biomarker." (PMID 37504302, 2023). "In high-grade glioma cell lines, PODNL1 has been demonstrated to stimulate cell proliferation and migration via the regulation of the Akt-mTOR axis." (PMID 37504302, 2023). "A recent study reported the unfavorable effects of PODNL1 overexpression in glioma overall survival." (PMID 34830454, 2021). "PODNL1, as a member of SLRP, has been found to highly express in high-grade glioma 3 and be a survival risk to glioma patients 4 according to previous studies." (PMID 33033506, 2020). "As expected, elevated PODNL1 expression predicted poor overall survival of glioma in both the IDH-Mu and IDH-Wt groups." (PMID 33033506, 2020). "Next, our study suggested that for the first time and as far as we knew, suppression of PODNL1 remarkably inhibited glioma cell proliferation, migration, EMT, and induced apoptosis." (PMID 33033506, 2020). "Firstly, we analyzed the expression levels of PODNL1 in WHO II-IV grade glioma tissues and compared the overall survival time between high and low PODNL1 expression groups through The Cancer Genome Atlas (TCGA) and CGGA databases." (PMID 33033506, 2020). "In summary, PODNL1 expression was negatively correlated with the prognosis of glioma patients, as well as along with the WHO grade II-IV." (PMID 33033506, 2020). "To evaluate the clinical significance of PODNL1 in glioma patients, we firstly analyzed the overall survival time through the two independent databases, TCGA and CGGA." (PMID 33033506, 2020). "In our study, we found that PODNL1 expression was negatively correlated with the prognosis of glioma patients from both TCGA and CGGA databases." (PMID 33033506, 2020). "Analyses combining the TIDE platform and Methsurv Database demonstrated that the survival prognosis, CTL infiltration level and T cell dysfunction were affected by PODNL1 methylation in multiple cancers, among which glioma was most significantly affected by methylation." (PMID 37504302, 2023). "In addition, PODNL1 knockdown suppressed glioma cell proliferation, migration, as well as inducing apoptosis." (PMID 33033506, 2020). "Moreover, PODNL1 promoted aggressive glioma behavior by activating Akt/mTOR pathway, providing a novel therapeutic target for glioma." (PMID 33033506, 2020). "Thus, we supposed that PODNL1 aggravated malignant behaviors through Akt/mTOR pathway in glioma cells." (PMID 33033506, 2020). "Our study aimed to identify the function of PODNL1 in glioma progression." (PMID 33033506, 2020). "Furthermore, we detected the expression level of PODNL1 in an astrocyte cell line and several human glioma cell lines, which suggested that most of the glioma cells highly expressed PODNL1 whereas one fifth expressed lower than astrocytes." (PMID 33033506, 2020). "Importantly, Yan et al3 have reported PODNL1 is overexpressed in high-grade glioma and Shergalis et al4 have indicated that PODNL1 expression is negatively correlated with overall survival." (PMID 33033506, 2020).
glioma (continued). "Therefore, our study focused on the function and regulatory mechanism of PODNL1 in glioma." (PMID 33033506, 2020). "Considering PODNL1 promoted glioma cell migration, we wondered if PODNL1 could regulate EMT." (PMID 33033506, 2020). "Nevertheless, both the biological function and mechanism of PODNL1 in glioma remain unclear." (PMID 33033506, 2020). "Moreover, most of these phenotypes showed the opposite trend after PODNL1 overexpressed in glioma." (PMID 33033506, 2020). "Moreover, the glioma cell growth and migration suppressed by PODNL1 knockdown could be partially rescued using Akt activator." (PMID 33033506, 2020). "Furthermore, we also demonstrated that PODNL1 was essential for the expression of the mesenchymal-related biomarkers in glioma cells, evidenced by remarkably promoting of vimentin, N-cadherin, snail and fibronectin expression after PODNL1 overexpressed, and vice versa." (PMID 33033506, 2020). "Another factor that may determine LGG aggressiveness in low methylation groups of these PODNL1 CpGs could involve the AKT signaling pathway, which we found to be enriched in this group, as previous studies reported the association between phosphorylation of AKT and glioma aggressiveness." (PMID 34830454, 2021).
ovarian carcinoma (3 papers, 2020 to 2025). A malignant neoplasm originating from the surface ovarian epithelium. "Studies have shown that high PODNL1 expression is associated with poorer overall survival in ovarian cancer." (PMID 41465326, 2025). "Currently, several studies have indicated that PODNL1 acts as a biomarker of prognosis in ovarian cancer." (PMID 33033506, 2020).
glioblastoma (2 papers, 2021). The most malignant astrocytic tumor (WHO grade IV). "Applying Reboot on data from 154 glioblastoma patients, we identified a three-gene signature (IKBIP, OSMR, PODNL1) whose increased derived risk score was significantly associated with worse patients’ prognosis." (PMID 34316711, 2021). "Previously, PODNL1 mRNA overexpression was reported to be associated with unfavorable OS in LGG and glioblastoma." (PMID 34830454, 2021).
acute myeloid leukemia (1 paper, 2023). Acute myeloid leukemia (AML) is a group of neoplasms arising from precursor cells committed to the myeloid cell-line differentiation. "Finally, in most tumors, PODNL1 expressions were not significantly correlated with TMB and MSI, only both positively correlated in THCA, negatively with TMB in KIRP, HNSC, and negatively with MSI in TGCT and acute myeloid leukemia (LAML)." (PMID 37504302, 2023).
astrocytoma (1 paper, 2021). "This indicates the possible demethylation of PODNL1 during grade progression and its role in astrocytoma aggressiveness." (PMID 34830454, 2021). "We further investigated the immune cell infiltration levels of 24 immune cell types within PODNL1 high/low oligodendroglioma and astrocytoma separately for all four CpGs, and found that there was increased immune cell infiltration in the low methylation groups of these CpGs within both LGG subtypes." (PMID 34830454, 2021). "Collectively, these results indicate that PODNL1 methylation may affect immune checkpoint blockade therapy response in both astrocytoma and oligodendroglioma in varying degrees." (PMID 34830454, 2021).
bladder cancer (1 paper, 2024). "Additionally, PODNL1 expression is significantly linked to the EMT pathway in bladder cancer." (PMID 39935693, 2024).
tumor (7 papers, 2019 to 2025). "Meanwhile, it was found that the H-score of PODNL1 in tumor tissues was significantly higher than that in adjacent normal tissues." (PMID 37504302, 2023). "Analysis of clinical stages in pan-cancer presented the results that the expression levels of PODNL1 increased with tumor development as its expression levels differed significantly between early (I and II) and advanced (III and IV) stages in multiple cancers." (PMID 37504302, 2023). "Our systematic study indicates that PODNL1 promotes tumor progression by activating tumor-promoting TGF-β signaling, involving the formation and maintenance of uncontrolled inflammatory EMT and ECM remodeling in the TME." (PMID 37504302, 2023). "At present, a number of studies have revealed the promoting role of PODNL1 in tumor proliferation and EMT." (PMID 37504302, 2023). "In the present study, we found that PODNL1 was highly expressed in tumor tissues in 15 types of cancers and its high expression was significantly associated with more advanced stages and poor prognosis in multiple types of cancers." (PMID 37504302, 2023). "Meanwhile, GSVA of cancer hallmark gene sets showed positive correlation with the PI3K-AKT-mTOR pathway, indicating that PODNL1 may involve regulating the switch of downstream pathways to induce pro-tumor effects." (PMID 37504302, 2023). "Put together, both the methylation and the related LincRNAs may participate in the complex regulatory network of PODNL1 during tumor progression." (PMID 37504302, 2023). "Our study has laid a foundation for further elucidating the molecular mechanisms of PODNL1 related regulatory network in tumor progression and developing PODNL1 as a potential tumor matrix-mediated biomarker for immunotherapy and prognosis in a pan-cancer setting." (PMID 37504302, 2023). "Our systematic study indicates that PODNL1 plays an important role in the complex regulation network of tumor progression, and lays a foundation for further exploration to develop PODNL1 as a valuable matrix-mediated biomarker for cancer immunotherapy and prognosis in a pan-cancer setting." (PMID 37504302, 2023). "Furthermore, high PODNL1 expressions were positively related with the regulation of tumor-promoting TGF-β signaling through downregulating SMAD2/3:4 heterotrimer regulations transcription and up-regulating the pathway restricted SMAD protein phosphorylation." (PMID 37504302, 2023). "As DFS indicates tumor aggressiveness through faster recurrence, we firstly analyzed the prognostic effects of PODNL1 mRNA in the DFS of all TCGA cancers, where PODNL1 mRNA overexpression was associated with significantly unfavorable DFS in four TCGA cancers including ACC, KIRC, KIRP, and LGG." (PMID 34830454, 2021). "Our findings from the differential gene and protein expression analysis suggest that the aggressive tumor behavior in hypomethylated PODNL1 CpGs may involve increased inflammatory pathways and immune cell infiltration levels." (PMID 34830454, 2021). "Suppression of PODNL1 dramatically reduced the tumor weight compared with the empty vector control." (PMID 33033506, 2020). "We identified four PODNL1 CpG sites, cg07425555, cg26969888, cg18547299, and cg24354933, which were associated with unfavorable overall survival (OS) and disease-free survival (DFS) in univariate and multivariate analysis after adjusting for age, gender, tumor-grade, and IDH1-mutation." (PMID 34830454, 2021). "The expression levels of PODNL1 were positively correlated with Immune Score, ESTIMATE score and stromal score, and negatively with tumor purity in 16, 25, 28, and 24 types of cancers, respectively." (PMID 37504302, 2023). "Previous studies showed that the knockdown of PODNL1 in the cell lines of GBM and BLCA can significantly influence the malignant biological behavior of tumor cells, including EMT and high proliferation." (PMID 37504302, 2023).
tumor (continued). "The podocan-like protein 1 (PODNL1), an important member of the small leucine-rich proteoglycans (SLRP) family, is a crucial component of the tumor microenvironment (TME)." (PMID 37504302, 2023). "The common upregulated genes in metastasis and primary tumor include epiphycan (EPYC), collagen type X alpha chain 1 (COL10A1), fibronectin type III domain containing 1 (FNDC1) and podocan-like protein I (PODNL1), which are mainly extracellular matrix related genes." (PMID 31600962, 2019). "Similarly, herein, PODNL1 was demonstrated to be involved in maintaining the CAF-TGF-β signaling loop in TME, and then might promote the continuous activation of EMT cascades and generated tumor immune evasion." (PMID 37504302, 2023). "Thus, we report that low PODNL1 methylation, specifically of CpG sites cg07425555, cg26969888, cg18547299, and cg24354933, may be a key factor in the modulation of immune infiltrates in the LGG tumor microenvironment, affecting its aggressiveness and prognosis." (PMID 34830454, 2021). "Other differences were also detected between the two types of tumor, specifically the lack of expression of KERA and the appearance of certain levels of PODNL1, but in both cases these alterations were limited to some patients." (PMID 34440771, 2021). "Neither NYX nor PODNL1 mRNA was detected in either tissue type, while around 50% of healthy tissue samples showed variable levels of CHAD transcription, though it was totally absent in tumor tissue." (PMID 34440771, 2021).
cancer (3 papers, 2021 to 2023). A tumor composed of atypical neoplastic, often pleomorphic cells that invade other tissues. "In our study, the methylation level of the PODNL1 site CG10729062 was found to be associated with OS in various cancers." (PMID 37504302, 2023). "In-depth demonstration of molecular mechanisms indicated that PODNL1 expressions were notably positively correlated with cancer-associated fibroblast (CAF) infiltration levels in 33 types of cancers." (PMID 37504302, 2023). "This is also testified with our findings in the present study that the heterogeneity of cancer genotype–phenotype cross-talking was associated with PODNL1, the important SLPR member in ECM." (PMID 37504302, 2023). "We explored the association between PODNL1 methylation levels and a range of immune cell infiltration levels across TCGA cancers." (PMID 34830454, 2021). "Additionally, the heterogeneity of cancer genotype–phenotype cross-talking was also observed associated with PODNL1." (PMID 37504302, 2023). "Meanwhile, the expression levels of PODNL1 in nine types of cancers were significantly downregulated." (PMID 37504302, 2023). "In the groups with high expression levels of PODNL1, we observed the extensive enrichment of CAFs in all 33 types of cancers and significant inhibition of canonical cascades and activation of non-canonical cascades of TGF-β signaling." (PMID 37504302, 2023). "Single-cell transcriptome analyses and immunofluorescence validations indicated that PODNL1 was predominantly expressed in the cancer cells and CAFs in various cancers." (PMID 37504302, 2023). "Then, our further analyses of single-cell transcriptomes showed that PODNL1 expression was mainly enriched in the cancer cells of BLCA, GBM, HNSC, KIRC, and OV, and in the CAFs in BLCA and HNSC as well." (PMID 37504302, 2023). "In adaptive immune cells, the infiltration levels of CD8 + T cells were found negatively correlated with the PODNL1 expressions in 13 types of cancers, and positively correlated in six types of cancers." (PMID 37504302, 2023). "A series of gene sets were adopted to examine the potential relevance of PODNL1 expression to cancer immunotherapy." (PMID 37504302, 2023). "Further single-cell sequencing analyses in five cancers (BLCA, GBM, HNSC, KIRC and GBM) indicated that PODNL1 was highly expressed in cancer cells in all included cancers as well as in CAFs of BLCA and HNSC." (PMID 37504302, 2023). "While current research primarily focuses on PODNL1’s role in cancer development and progression, its potential influence on cell proliferation and differentiation is evident." (PMID 38017403, 2023). "Among them, the Pan_F_TBRs, EMT and angiogenesis had significant positive correlations with PODNL1 expressions in almost all the cancers." (PMID 37504302, 2023). "PODNL1 was significantly correlated with the poor prognosis and immunotherapeutic responses in various cancers." (PMID 37504302, 2023). "Significant correlations were observed between the expression levels of PODNL1 and immune infiltration at a pan-cancer scale." (PMID 37504302, 2023). "Interestingly, our study showed a concordant indication by presenting a positive correlation between CD276 and PODNL1 expressions in pan-cancer." (PMID 37504302, 2023). "The genome-wide co-expression analyses showed that the expression levels of collagen genes (COL1A1, COL1A2, COL5A1, COL5A2, COL8A1 and COL8A2) and LincRNAs (Linc01614 and Linc01711) were significantly positively correlated with PODNL1 expressions in various cancers." (PMID 37504302, 2023). "In short, our results indicate that PODNL1 may involve collagen dysfunction in ECM remodeling in TME in a pan-cancer setting." (PMID 37504302, 2023). "Furthermore, Linc01614 was also found significantly positively co-expressed with PODNL1 in multiple types of cancers." (PMID 37504302, 2023).
cancer (continued). "Combined with previous studies, such results indicate that PODNL1 could serve as a novel potential biomarker to guide prognosis predictions and individualized therapies in cancers." (PMID 37504302, 2023). "Targeting PODNL1, a systematic exploration into the TCGA datasets, reconciling with the analyses of single-cell transcriptomes and immunotherapeutic cohorts in cancers, and validation by tissue microarray-based multiplex immunofluorescence staining was performed." (PMID 37504302, 2023). "The present study comprehensively uncovered the correlations of the class V SLRP member PODNL1 expression with the prognosis, immunotherapeutic response, TME immune infiltration, co-expression networks, mutation landscape and epigenetic regulation in a pan-cancer setting." (PMID 37504302, 2023). "Further exploration via the cox proportional hazards model demonstrated that significant correlations between the expression levels of PODNL1 and OS, PFS, DFS, and DSS in various cancers." (PMID 37504302, 2023). "We found that both the protein levels of PODNL1 and FAP were higher in TME, and PODNL1 protein was especially highly expressed in cancer cells." (PMID 37504302, 2023). "The GSEA confirmed that PONDL1 expressions significantly positively correlated with the pathways in cancers and focal adhesion in six types of cancers including LGG, GBM, KIRC, BLCA, KIRP and OV, which all exhibited a poor prognosis in the PODNL1 high expression groups." (PMID 37504302, 2023). "Furthermore, the DIA of TMA-based multiplex immunofluorescence staining revealed the protein co-expression relationship between PODNL1 and FAP, an important CAFs marker, in 20 types of cancer." (PMID 37504302, 2023). "Particularly, the positive correlations of PODNL1 expressions with such collagens as collagen type 1 alpha 1 chain (COL1A1), COL1A2 and collagen type V alpha 1 chain (COL5A1) were found in over 30 types of cancers." (PMID 37504302, 2023). "Moreover, the infiltration levels of B cells presented significant negative correlations with PODNL1 expressions in the majority of pan-cancer except THCA, KIRP, liver hepatocellular carcinoma (LIHC) and PCPG." (PMID 37504302, 2023).
PODNL1 also shares sentences with these, for which no sentence is quoted: adrenocortical carcinoma (1 paper); bacterial infection (1); brain tumor (1); breast carcinoma (1); breast-invasive carcinoma (1); cholangiocarcinoma (1); colon adenocarcinoma (1); diffuse large B-cell lymphoma (1); esophageal carcinoma (1); lung adenocarcinoma (1); lung squamous cell carcinoma (1); lymphoid neoplasm (1); melanoma (1); mesothelioma (1); oligodendroglioma (1); pancreatic adenocarcinoma (1); pheochromocytoma and paraganglioma (1); rectum adenocarcinoma (1); retinal diseases (1); sarcoma (1); thymoma (1); uterine corpus endometrial carcinoma (1).